TLR4 (toll like receptor 4)
Diseases named in the same sentence as TLR4 in open-access papers (continued):
Sharing a sentence is not in itself a finding about the gene and the disease.
diabetes (continued). "AGEs may exacerbate inflammation in periodontitis by activating both RAGE and TLR4, clarifying the molecular link between diabetes and severe periodontal destruction." (PMID 41369400, 2025). "During the diabetes modeling process via STZ intraperitoneal injection, TLR4 gene knockout was found to postpone and alleviate the mice from reaching the criteria of type 2 diabetes, and the female mice were less prone to reaching the diabetes criterion." (PMID 38275739, 2024). "TLR4 expression is increased in a wide range of cell types such as renal proximal tubule cells, retinal endothelial cells, and monocytes from patients with diabetes." (PMID 38525707, 2024). "The dysregulation of TLR4 signalling in diabetes complicated by dyslipidaemia may contribute to the pathogenesis and exacerbation of diabetic neuropathy, and TLR4 can be a therapeutic target for diabetic neuropathy." (PMID 38525707, 2024). "With two STZ injections, 37% WT and 17% TLR4−/− male mice reached the diabetes criterion." (PMID 38275739, 2024). "Finally, we simulated the high-glucose environment of diabetes to show that elevated glucose levels enhance TLR4 activation by a DAMP known to be upregulated in diabetes." (PMID 36982926, 2023). "It should be noted that since the serum levels of HMGB1 are increased in diabetic individuals, TLR4 activation by this DAMP might also play a role in impaired skin wound healing in diabetes." (PMID 36982926, 2023). "TLR2 and TLR4 are involved in the progression of asthma and type 2 diabetes mellitus (T2DM)." (PMID 36836906, 2023). "Many complications of diabetes have been connected to TLR4-mediated chronic inflammation." (PMID 36656815, 2023). "Diabetes and Alzheimer’s disease have both been recently related to TLR4." (PMID 36656815, 2023). "By reducing oxidative stress, inflammation, and apoptosis, the TLR4/NF-κB signal pathway may reduce hyperglycemia and diabetes-induced cardiomyopathy." (PMID 38259289, 2023). "This up-regulation of TLR4-mediated inflammation has been found in the diabetic heart and repression of TLR4 benefits to lower lipid accumulation and to ameliorate cardiac function in diabetes." (PMID 36187088, 2022). "TLR4 plays a key role in the treatment of diabetes and its complications." (PMID 35845591, 2022). "Diabetes increased TLR4-mediated inflammation, whereas DP inhibited the protein expression of the TLR4 pathway (TLR4, Myd88, IRAK1, and TRAF6) and reduced the mRNA expressions of IL-1β, IL-1α, IL-6, and TNF-α and the protein expressions of TNF-α, IL-1β, and COX-2." (PMID 35463063, 2022). "Toll-like receptor 4 (TLR4) inhibitor was administrated to type 2 diabetes mellitus (T2DM) AS rats." (PMID 35069982, 2022). "The EPE might reduce the production of proinflammatory cytokines via TLR4 pathways and improve diabetes-induced male infertility." (PMID 33996978, 2021). "The expression and function of TLR4 also increased in monocytes in diabetes patients." (PMID 33478014, 2021). "While the pathogenesis of diabetes-induced high blood pressure (BP) is not entirely clear, current evidence suggests that Toll-like receptor 4 (TLR4) is a key player in the mechanisms associated with hypertension." (PMID 32694567, 2020). "We have gathered sufficient evidence suggesting TLR4 is involved in the pathogenesis of diabetes in NOD mice and that its blockade prevents the activation, cellular division, proliferation and differentiation of T lymphocytes into Th1 and Th17 effector lymphocytes." (PMID 31852918, 2019). "In this context, TLR4 could be a major player in diabetes pathogenesis, since it recognizes bacterial LPS but also damage associated molecular patterns (DAMPs)." (PMID 31852918, 2019). "Consequently, scientists have correlated the TLR4 signaling pathway with the innate immune system and microvascular inflammatory response in people with diabetes, rendering this pathway a favorable target for anti-inflammatory treatments for DN." (PMID 31191309, 2019).
diabetes (continued). "Our working hypothesis is that TLR4 may be involved in the pathogenesis of diabetes and that its blockade may prevent or delay the onset of autoimmunity." (PMID 31852918, 2019). "Moreover, it has recently been suggested that the crosstalk between TLR-4 and dipeptidyl peptidase-4 (DPP-4)-incretin system is significantly associated with diabetes and CAD." (PMID 30654523, 2019). "This is again supportive for the role of TLR4 activation in diabetes progression." (PMID 29426925, 2018). "The upregulation of the TLR4 expression has been demonstrated in diabetic mice, and the silencing of the TLR4 gene could control cardiac apoptosis in diabetes." (PMID 29371661, 2018). "The role of TLR4 in diabetes mellitus has been receiving much attention at present." (PMID 29097792, 2017). "The dysregulation of TLR-4 signaling pathway had a close relationship with development and progress of various diseases, such as nephrotic syndrome, nephritis, renal insufficiency, hypothyroidism, systemic lupus erythematosus, diabetes and so on." (PMID 28524080, 2017). "Intravitreal injections of anti-Il-1β and anti-Tlr4 neutralizing antibodies to animals with STZ-induced diabetes significantly reduced retinal Lgals1 expression (anti-Il-1β, fold change = 1.96; anti-Tlr4, fold change = 1.41) compared to normal IgG treatment (fold change = 3.55)." (PMID 29170525, 2017). "TLR4 plays an important role in diabetes and diabetic complications." (PMID 28785380, 2017). "Inhibition of receptor for advanced glycation end products (RAGE) has also proven effective in a rodent model of diabetes; however, other targets of TLR4 may also be effective." (PMID 28348460, 2017). "A recent study disclosed that FOXO1 supports inflammation during diabetes by increasing the expression of TLR4, recommending that FOXO1 may function as an essential regulator of inflammatory reactions during obesity and diabetes mellitus." (PMID 26956801, 2016). "Further, the data demonstrate that the reduced expression of TLR4 on T cells was correlated with enhanced CFR suggesting that TLR4 lymphocytes may be related to cardiac functions in diabetes." (PMID 27095356, 2016). "The authors found that deficiency of TLR4 but not of TLR2 alleviates several diabetes-induced changes, including albuminuria, tubulointerstitial fibrosis, kidney inflammation and tubular apoptosis." (PMID 26398934, 2015). "Among its functions are activations of NADPH oxidase, toll like receptors 4 (TLR4), and advanced glycation end products (AGEs) receptors, which are important signallling pathways in pathogenesis of micro- and macrovascular complications of diabetes." (PMID 25995771, 2015). "Moreover, in TLR2-/- and TLR4-/- mice induced with diabetes, there was an amelioration of glomeruli ICAM-1 expression versus wildtype diabetic mice." (PMID 25303153, 2014). "Thus, the discrepancies observed then suggest that TLR4 expression is regulated both on the mRNA level and on the protein level in diabetes and that the upregulation on the transcriptional level doesn’t correlate with the amount of protein finally expressed." (PMID 24594974, 2014). "Clearly, given the likelihood for hyperglycemia to play a central role in cardiac malfunction during diabetes, the impact of hyperinsulinemia on TLR4 expression during metabolic diseases, such as in pre-diabetic and diabetic heart disease, requires investigation." (PMID 25101057, 2014). "Furthermore, the data suggests that the capacity to respond is modified in diabetes as more TLR4 positive macrophages are present in the diabetic tissue." (PMID 24594974, 2014). "This maximal TLR4 expression in the fluctuating glucose limb also correlated to maximal increase in NF-ĸB activation and downstream expression of chemokines and cell adhesion molecules implicating the involvement of TLR4 in vascular complications of diabetes." (PMID 25303153, 2014).
diabetes (continued). "In addition, upregulated TLR4 expression is likely to lead to disease-resistant effects, and TLR4 has a proinflammatory role in the occurrence of diabetes and its complications." (PMID 24348797, 2014). "With the enhanced number of macrophages expressing TLR4 showing an activated phenotype and the previously demonstrated co-localization of macrophages to β-cells in diabetes, the present study further emphasis the emerging role of auto-inflammation in the progression of T2D." (PMID 24594974, 2014). "Moreover, we have uniquely shown that there is a marked reduction in glomerular ICAM-1 expression in TLR2-/- and TLR4-/- murine models compared to wildtype mice induced with diabetes." (PMID 25303153, 2014). "CCL2 expression, macrophage recruitment and fibrosis were all attenuated in TLR4−/− mice with diabetes.This result is consistent with a recent study in humans where over expression of TLR4 in renal tubules correlated with monocyte and macrophage accumulation in diabetic kidneys." (PMID 24842252, 2014). "Therefore, in the present study we aimed to find diabetic foot ulcer (DFU) risk associated with rs4986790, rs4986791, rs11536858, rs1927911, and rs1927914 in the TLR4 gene in type 2 diabetes mellitus (T2DM) patients." (PMID 23936790, 2013). "Inflammatory mediators including MMP9, RAGE and TLR4 in diabetes might contribute the increased initiation and formation of aneurysm and arteriosclerosis." (PMID 23844137, 2013). "Triad3A (RNF216) was significantly higher in diabetes and may have contributed to reduced levels of TLR4 protein." (PMID 23149823, 2013). "In addition, TLR4 initiates inflammation in diabetics and plays an important role in arteriosclerosis by inducing inflammation responses." (PMID 23844137, 2013). "We therefore hypothesised that TLR4-deficient NOD mice, showing accelerated diabetes development, exhibit decreased Treg cell activity." (PMID 24086519, 2013). "To clarify this, we measured TLR4 levels in mice in the early stages of diabetes." (PMID 21159162, 2010). "However, 214-EVs completely abolished the diabetes-induced elevation of TLR4 and NFκB expression." (PMID 40950414, 2025). "In addition, Morchella esculenta polysaccharide (MEP) significantly ameliorated high-fat diet-induced diabetes by augmenting Lactobacillus, inhibiting enterococci, and modulating inflammatory cascade responses, including Toll-like receptor 4 (TLR4), COX-2, and NF-κB." (PMID 41334341, 2025). "However, this function is disrupted by TLR4 activation or during diabetes progression." (PMID 40791590, 2025). "Conversely, some studies suggest that TLR4 deficiency may not consistently confer protection and, under certain conditions, may even accelerate diabetes development." (PMID 40969771, 2025). "This might partly reflect a sort of specific localization and will require further investigations to find out whether TLR4 could be a direct target of miRNA-146a in diabetic kidneys and whether 6-gingerol could inhibit TLR4 expression via miRNA-146a up-regulation or a different mechanism." (PMID 39033184, 2024). "Thus, we postulated that the synergistic induction of TLR4 and its activation by hyperglycaemia and oxLDL treatment could be a potential mechanism of neuronal injury in diabetes." (PMID 38525707, 2024). "Thereby, it was speculated that TLR4 deletion might boost the upregulation of cardiac fatty acids metabolism via AMPK activation following diabetes and indicate a potentially significant relation of TLR4 and AMPK in the progression of diabetic cardiomyopathy and dysfunction." (PMID 36721803, 2023). "However, it is still rather unclear whether NLRP3 inflammasome activation is regulated by TLR4 during CIRI in the context of diabetes." (PMID 35419168, 2022).
diabetes (continued). "In conclusion, this study systemically revealed that diabetes-associated hyperglycemia markedly deteriorated liver IR damage via activation of the ER stress-ATF6-CHOP signaling pathway, which subsequently inhibited β-catenin signaling and promoted TLR4-mediated inflammatory responses." (PMID 35289326, 2022). "Thus, inhibition of TLR-4 could be a potential therapeutic target in diabetes and its potential vascular complications through suppressing inflammation and interstitial macrophage infiltration." (PMID 30534206, 2018). "Knock-out of TLR4 could attenuate the pro-inflammatory state of diabetes in mice." (PMID 29535629, 2018). "Inactivation of aberrant TLR4 function during metabolic disease may provide novel therapeutic targets for the treatment or prevention of cardiovascular diseases in individuals with diabetes." (PMID 25101057, 2014). "TLR4 activation and downstream cytokine production may lead to the development of diabetes." (PMID 24348797, 2014). "Furthermore, knockout of tlr4 attenuated the proinflammatory state of diabetes in animal models." (PMID 24779014, 2014). "The objective of the present work was to evaluate the association of TLR4 single nucleotide polymorphisms (SNPs) rs4986790, rs4986791, rs11536858 (merged into rs10759931), rs1927911, and rs1927914 with increased diabetic foot ulcer (DFU) risk in patients with type 2 diabetes mellitus (T2DM)." (PMID 23936790, 2013). "Both studies report that TLR4-deficient NOD mice develop diabetes but it was not described whether there was acceleration of diabetes development compared to the parental NOD mouse strain." (PMID 24086519, 2013). "However, data examining the mechanism of TLR2 and TLR4 expression and function of cornea in diabetes are unknown." (PMID 22219634, 2011). "HMGB1 is a typical DAMP that engages TLR4 to activate NF‐κB and prime the NLRP3 inflammasome, thereby amplifying IL‐1β–driven inflammation; diabetes‐related AGEs and ROS further potentiate NLRP3 activation and pyroptosis, delaying epithelial repair." (PMID 41503166, 2026). "High glucose activates Toll-like receptor 4 (TLR4) signaling in VSMC, a key component of innate immunity activated in diabetes, resulting in increased ROS production." (PMID 40940776, 2025). "A similar mechanism operates in diabetes mellitus, where HMGB1 contributes to disease progression by activating the TLR4/endothelial nitric oxide synthase signaling pathway." (PMID 40362460, 2025). "Compared with Ctrl mice, the expression of TLR4, P-NF-κB and NLRP3 in the kidney of diabetes mice were markedly escalated (p < 0.01)." (PMID 40176887, 2025). "Tripdiolide treatment significantly decreased TLR4 by 45.3%, P-NF-κB by 54.9%, and NLRP3 by 30.7% in the kidney of diabetes mice (p < 0.05)." (PMID 40176887, 2025). "To assess the effect of TLR4 on the overproduction of corticosterone by diabetic mice, we treated the mice with TLR4 antagonist TAK-242 and induced diabetes in the TLR4 mutant mice C3H.HeJ." (PMID 40496562, 2025). "The expressions of IL17A, ACE, TLR4, and IL6 are up-regulated with diabetes that promote the progression of gangrene, whereas the expressions of FGF2 and IGF1 are down-regulated." (PMID 40657379, 2025). "In accordance with previous findings, diabetes has led to a significant increase in IL6 concentration in serum and TLR4 gene expression in cecal tissue samples." (PMID 38626052, 2024). "In summary, NF-kβ/ TLR-4 and SERCA/ Ca2+ pathways contribute to the pathophysiology of Type 2 Diabetes Mellitus (T2DM) by regulating β-cell functions and apoptosis." (PMID 38778421, 2024). "Further, TLR-2, TLR-4, TLR-5, TLR-9, and others play a critical role in the pathogenesis of IBD, and TLR-2, TLR-1, TLR-4, TLR-6, and TLR-7 contribute to diabetes." (PMID 39328924, 2024). "Diabetes also induces an increase in the permeability of the blood–brain barrier (BBB) and Toll-like receptor 4 (TLR4) expression in the hippocampus." (PMID 37892186, 2023).
diabetes (continued). "↑Serum insulin level, Th2-bias ed. cytokine response; ↓Onset and the development of diabetes, Th1 pro-inflammatory cytokines levels, MHC class II and CD86, TLR4 and downstream molecules’ expression in the pancreas." (PMID 37396125, 2023). "Patients with type 2 diabetes mellitus (T2DM) also showed significantly elevated serum CML and hs-CRP with a remarkable increase in TLR-4 expression and IL-6 and TNF-α, suggesting that high level of CML is associated with pro-inflammatory cytokines." (PMID 36077532, 2022). "Patients with type 1 diabetes mellitus (T1DM) showed significantly higher serum levels of CML and high-sensitivity C-reactive protein (CRP) than the control group via an increase in Toll-like receptor 4 (TLR-4) expression in monocytes." (PMID 36077532, 2022). "For instance, in diabetes, propolis helped increasing TLR-2 and TLR-4, thus activating the B and T function, improving the lipid profile, reducing the ROS and modulating the HbA1C and FSG glycemic factors." (PMID 35047540, 2021). "LPS is a classic toll-like receptor 4 (TLR-4) agonist and was selected in part due to recent work by others showing LPS stimulation generates MSC exosomes that promote wound healing in a diabetes model." (PMID 34407878, 2021). "In this study, the percentage and number of selected lymphocytes expressing TLR2, TLR4, and TLR9 receptors in children with type 1 diabetes mellitus were assessed." (PMID 34830017, 2021). "For example, the OS-induced inflammation basically shares the common mechanism of TLR4/NF-κB and TLR4/MAPK pathways in diabetes and IRI." (PMID 33928135, 2021). "Studies in disparate fields, including diabetes and UV irradiation of melanocytes, point towards several upstream signaling proteins, such as NF-κB, STAT1, and TLR-4." (PMID 33256011, 2020). "We also demonstrated the anti-inflammatory effect ATRA by suppressing the toll-like receptor 4 (TLR4) and the nuclear factor-кB (NF-кB) signaling in glomeruli and proximal tubules in a model of diabetes." (PMID 31557800, 2019). "Because the activation of TLR4 may lead to the stimulation of the transcription factor NF-κB and, as a consequence, to the intensification of inflammatory cytokine production, in our study, we investigated the impact of diabetes on the phosphorylation of the p65 NF-κB subunit." (PMID 31197747, 2019). "Both TLR4 and CXCR4 are G protein-coupled receptors and can bind to the HMGB1 in cytoplasm, which expression level is elevated in diabetes." (PMID 30647535, 2018). "The binding of TLR4 and CXCR4 to HMGB1 is crucial to trigger chronic inflammation response in diabetes." (PMID 30647535, 2018). "In the monocytes of type 1 and type 2 diabetes patients, levels of TLR2, TLR4, and other TLR-signaling components (e.g., MyoD88 and NF-κB) were increased." (PMID 28824448, 2017). "However, TLR4 plays a negative role under diabetic conditions, as indicated by the fact that skin wound healing is significantly improved in TLR4-deficient mice with induced diabetes compared to healing in diabetic wild-type animals." (PMID 28542370, 2017). "Taken together, our data indicate that resistin induces IR and hypertension in mice via a mechanism dependent on TLR4 and RAS, suggesting that resistin is a crucial factor linking diabetes and hypertension." (PMID 26917360, 2016). "In NOD mice, weekly injections of many different TLR ligands, including poly(I:C) (TLR3 agonist), LPS (TLR4 agonist), or P40 protein from Klebsiella (TLR2 agonist), can block diabetes development if started at weaning." (PMID 26124756, 2015). "In this study, we report elevated expression of TLR4, its endogenous ligands and downstream cytokines, chemokines and fibrogenic genes in diabetic nephropathy in WT mice with streptozotocin (STZ) diabetes." (PMID 24842252, 2014). "Overexpression of TOLLIP in diabetes was yet another possible mechanism for inhibition of TLR2- and TLR4-mediated NFκB activation." (PMID 23149823, 2013).